INS (insulin)
Diseases named in the same sentence as INS in open-access papers (continued):
Sharing a sentence is not in itself a finding about the gene and the disease.
Obesity (continued). "Several studies have highlighted the beneficial action of chemical induction of HO-1 to lower body weight, normalize insulin resistance and improve the adipokine profile in rodent models of obesity." (PMID 28287466, 2017). "With increasing BMI of ND subjects, insulin and glucagon contents respectively tended to increase and decrease, resulting in a lower glucagon/insulin ratio in obesity." (PMID 28887444, 2017). "This study was aimed at determining the effects of dietary administration of lipoic acid on a HFD-induced obesity model in terms of (a) insulin signaling, (b) brain glucose uptake and neuronal- and astrocytic metabolism, and (c) synaptic plasticity." (PMID 28710347, 2017). "Several other studies in HFD induced obesity model have reported increased levels of corticosterone and their metabolites in obese rats which along with insulin increased the fat stores and contributed to obesity due to high caloric intake." (PMID 28253924, 2017). "Critically, these effects are blunted in obesity with evidence that hypothalamic insulin resistance is driven by visceral fat and frontal insulin resistance by peripheral insulin sensitivity." (PMID 28400713, 2017). "Exogenous administration of insulin recovers both the hyperphagia and weight gain, suggesting that HI is required for the manifestation of obesity following the VMH lesion." (PMID 28466412, 2017). "Other studies have suggested that transgenic or pharmacological inhibition of HIF-1α in adipocytes prevents the onset of obesity from overfeeding and improves insulin sensitivity." (PMID 28725215, 2017). "Metformin is a potent anti-hyperglycemic agent used to treat T2D; however, several studies used metformin alongside intensive insulin therapy to treat patients with T1D and obesity." (PMID 28836234, 2017). "Obesity decreases the transport of insulin across the BBB, and this deficit can be reversed by starvation and caloric restriction." (PMID 28515688, 2017). "Recent epidemiological studies provided evidence that insulin, GH/IGF-1, and adiponectin signaling are molecular pathways interconnected with each other and linking obesity to metabolic diseases risk." (PMID 29036907, 2017). "We believe that increases in plasma insulin concentrations and hepatic FAS activities among the three obese groups were associated with the development of obesity via the consumption of long-term high-fat diets in the present study." (PMID 29048361, 2017). "Leukocyte cell-derived chemotaxin 2 (LECT2) is a hepatokine linking obesity to skeletal muscle insulin resistance." (PMID 28278265, 2017). "Accumulating evidence suggests that leptin and insulin are key molecules linking obesity with diseases of the lower intestine." (PMID 28170448, 2017). "Leptin, adiponectin, and insulin are indicators of body mass fats and energy imbalance and are present in obesity." (PMID 29234430, 2017). "Most studies have focused on the direct relationship between macrophages and obesity, meanwhile, important questions concerning the relationship between obesity, insulin, and CD4+ T cell type populations and plastic changes among them remain unaddressed." (PMID 28651594, 2017). "Resistin named for its ability to resist insulin action has an important link between obesity, insulin resistance and diabetes." (PMID 28806778, 2017). "Concurrent to an increase in NAFLD prevalence, there is an increase in the obesity epidemic and the correlated insulin-resistant state." (PMID 29358945, 2017). "Resistin impairs glucose tolerance and insulin action and inhibits adipogenesis in murine 3T3-L1 cells and has been proposed as an adipocyte-secreted factor that is believed to link obesity and type 2 DM." (PMID 28806778, 2017). "Under conditions of diet-induced obesity, Gpr88 ablation improved body lean content, weight recovery and feeding following fasting, insulin responsiveness and glucose tolerance." (PMID 28855710, 2017).
Obesity (continued). "Our data are also indicative of Ch25h expression where not only is it downregulated in the wake of obesity, but also its importance is mainly at the point of decision between insulin resistance and insulin sensitivity." (PMID 28299341, 2017). "Glucose homeostasis and insulin production are greatly determined by obesity and body fat distribution, however the pathogenesis of obesity-induced insulin resistance has not been fully elucidated." (PMID 29225702, 2017). "Collectively, numerous studies in humans have confirmed findings obtained from rodent model organisms that clearly point towards a major role of central insulin resistance in the dysregulation of energy homeostasis and the development of obesity in humans." (PMID 28592656, 2017). "Examinations were performed, including general physiological characteristics, obesity-related biochemical parameters, and insulin-signaling pathway-related proteins in the hypothalamus." (PMID 28684967, 2017). "However, several possible biological mechanisms that may underlie the association between obesity and prostate cancer death have been proposed, including mechanisms that involve insulin and the IGF-I axis, sex hormones, and inflammatory and oxidative stress pathways." (PMID 28701188, 2017). "Lactobacillus NK318.1 gavages also impeded HFD-mediated obesity and reduced sensitivity to insulin and glucoses." (PMID 28928739, 2017). "Previous study has demonstrated the polysaccharide of Angelica sinensis in ameliorating glucose and lipid metabolism disorders related to obesity, possibly due to interactions with insulin and serum inflammatory factors." (PMID 29098158, 2017). "This indicates that the metabolic programming, induced by malnutrition in early life, impairs insulin-glucose homeostasis to a greater extent than obesity per se." (PMID 28951790, 2017). "In obesity, the compromised glucose uptake into metabolic organs induces hyperglycemia in turn accelerating insulin production in beta cells." (PMID 28233125, 2017). "Together, the emerging research from both animals and humans converge on the idea that there are detrimental effects on brain insulin signaling as a result of obesity which are closely tied to peripheral metabolic dysfunction." (PMID 28507516, 2017). "Obesity-induced inflammation and ER stress is known to negatively impact insulin sensitivity and adipocyte functions in WAT20; however, little is known about its effect on BAT." (PMID 28067333, 2017). "In contrast, mice fed a HFD with Ilex latifolia Thunb exhibited normal blood insulin and glucose concentrations, suggesting the improvement of obesity-related insulin sensitivity and glucose homeostasis." (PMID 29116160, 2017). "Obesity-related inflammatory, oxidative, adipogenetic mechanisms and insulin signalling can be also concomitant to miRNAs deregulated expression." (PMID 28607629, 2017). "Obesity is believed to decrease insulin sensitivity through damaging insulin receptors in peripheral target tissue cell membrane, eventually leading to the failure of pancreatic β-cell function." (PMID 29125537, 2017). "In fact, obesity is an independently predicted factor of decreased incretin action, and integration of obesity and hyperglycemia additively impair insulin secretion by incretin." (PMID 28626771, 2017). "A pioneering study from Hotamisligil and Spiegelman identified adipocytes as source of TNFα in the WAT that ultimately impaired insulin signaling in obesity." (PMID 28233125, 2017). "Consistently, both Fsp27−/− and ob/ob×Fsp27−/− mice are resistant to diet-induced obesity, dyslipidemia, and hepatosteatosis and have improved insulin sensitivity." (PMID 27884961, 2017). "Research in rodent models of obesity and Type II Diabetes support this idea, demonstrating that learning and memory functions are selectively impaired in insulin resistant rodents compard to healthy controls." (PMID 28507516, 2017).
Obesity (continued). "In obesity, for example, altered epithelial permeability and permeation of the gut by LPS can lead to increased levels in the plasma and insulin-resistant states." (PMID 27908847, 2017). "Suggested factors linking obesity to kidney dysfunction include low-grade inflammation, insulin resistance and adipokine dysregulation." (PMID 28588299, 2017). "The induction of ER stress and steatosis precedes obesity and changes in insulin action and a sustained ER stress can worsen the metabolic dysregulation through activation of lipidogenic genes." (PMID 28540288, 2017). "Treatment with CUR alleviates obesity and periphery lipid accumulation, and improves insulin sensitivity in mice fed with high fat diet." (PMID 29046626, 2017). "In univariate analysis, of baseline parameters, measures of obesity, concentrations of fasting glucose, insulin, triglycerides, HDL cholesterol and liver enzymes, and liver fat content predicted liver fat content at 11.3 years." (PMID 29109528, 2017). "Human visceral AT is prone to inflammation in obesity because ofenhanced immune cell content and increased proinflammatory cytokine expression likeTNF-α that promotes insulin resistance in peripheral tissues." (PMID 28559441, 2017). "PKC zeta and GLUT4 proteins were not modulated by either a maternal or a post-weaning obesogenic diet, suggesting the effects of maternal obesity and offspring obesity are specific to a subset of insulin signalling proteins." (PMID 28338072, 2017). "We also give an overview of the pleiotropic factors involved in the regulation and dysregulation of the homeostatic hypothalamic system in the context of obesity, including hypothalamic inflammation as well as insulin and leptin resistance." (PMID 28592656, 2017). "This in vivo gain-of-function study indicates elevated hepatic Ch25h levels are able to improve insulin sensitivity and therefore induce a metabolically healthy form of obesity." (PMID 28299341, 2017). "Mechanisms underlying IR on the development of cardiovascular and all-cause mortalityare considered to be through the direct atherogenic action of insulin on vessel wall and/or indirect through obesity, blood pressure, lipids and metabolichomeostasis." (PMID 28811358, 2017). "Chemical induction of HO-1 has been demonstrated to prevent obesity, improve insulin sensitivity, and increase metabolism in numerous rodent models of obesity and diabetes." (PMID 28287466, 2017). "PIKE expression increases significantly in the adipose tissue and muscles of obese mice, whereas PIKE knockout mice are resistant to HFD-induced obesity due to improved insulin sensitivity as a result of increased AMPK activity." (PMID 28170448, 2017). "Larger scale future studies are required in order to determine how age, obesity, and insulin sensitivity/resistance are individually related to blood and brain bioenergetics." (PMID 29098063, 2017). "Our findings are in good agreement with reports demonstrating the role of ATP10A (formerly ATP10C), another class 5 P4-type ATPase, in diet-induced obesity, T2D and insulin-stimulated glucose uptake." (PMID 28542499, 2017). "The analysis of CNVs in six regions corresponded to five genes previously associated with obesity, LEPR (intron 2 and intron 3), NEGR1, ARHGEF4, CPXCR1, and INS, and four intergenic regions (1p36.33b, 12q15c, 15q21.1a, and 22q11.21d)." (PMID 28428959, 2017). "The guiding principle should be: ‘Overweight and obesity are determined by a hormonal imbalance characterized by a constant and sustained secretion of insulin, which results from particular dietary compositions." (PMID 28485680, 2017). "The obesity, high insulin levels and glucose intolerance leading to hyperglycemia, appeared to phenotypically recapitulate the human disease." (PMID 28640904, 2017). "Circulating insulin levels are elevated in each model of obesity, while glucagon was increased only in the db/db mice." (PMID 29038790, 2017).
Obesity (continued). "Another study, called MUFA in Obesity (MUFObes), shows that MUFA rich diet improves insulin and glucose concentrations and reduces the risk of weight regain." (PMID 27894098, 2017). "Remarkably, we found that the PG is also an organ that becomes resistant to insulin actions under an obesity condition and that this state is even more pronounced in the PG than in the liver." (PMID 28244645, 2017). "Here we show that PTPR-γ is a negative regulator of hepatic insulin signaling in both physiological and obesity/inflammation contexts." (PMID 29180649, 2017). "Macrophages are believed to be major sources of inflammatory cytokines with detrimental effects on insulin signaling in obesity." (PMID 28686216, 2017). "The FATZO mouse resulted from a cross of C57BL/6J and AKR/J mice followed by selective inbreeding for obesity, increased insulin and hyperglycemia." (PMID 28640904, 2017). "We identified for the first time that neutralising the ADAM19 metalloproteinase domain reduced high fat diet induced obesity and improved insulin sensitivity in obese and T2D mice." (PMID 28265178, 2017). "It is well known that systemic CLGI damages pancreatic beta cells, disrupts insulin action, and mediates glucose intolerance in obesity." (PMID 28536285, 2017). "Increased insulin signaling in steroidogenic factor 1-expressing neurons of the VMH during obesity has been shown to regulate adiposity in mice on a high-fat diet." (PMID 28466412, 2017). "In humans, other cross‐sectional studies have reported increases in some 23, 24 or all 25 saturated ceramides in insulin‐resistant subjects with obesity." (PMID 26916476, 2016). "Insr, the heterodimer genes coding for insulin signalling members, have been reported to be significantly reduced in obesity." (PMID 27456968, 2016). "Taking into consideration the close pathogenetic relationship between obesity and IR, the IR markers (insulin levels, C-peptide levels and HOMA-IR) and basal and postprandial glucose levels were measured on days 1 and 12 from MI onset." (PMID 26989445, 2016). "Orz has attracted attention as a functional food with several beneficial interactions in organism, particularly given its antioxidant, anti-obesity, and anti-inflammatory properties, as well as its ability to improve insulin resistance and hepatic metabolism." (PMID 27517904, 2016). "Circulating irisin is correlated to favorable metabolic profile, including reduced obesity, lower blood pressure and lower glucose levels, healthy lipid parameters, and increased insulin sensitivity." (PMID 26790404, 2016). "When the entire sample was evaluated together, α-MSH levels were negatively correlated with various parameters of obesity, including weight z-score, BMI, BMI z-score, BMI percentile, as well as insulin and CRP levels." (PMID 26758700, 2016). "As a result, we carried out this study to investigate the relationship between obesity and insulin sensitivity in Cameroonian women living with PCOS." (PMID 27672393, 2016). "We identified both these proteins with loss of phosphorylation suggestive of defects in insulin-stimulated signaling and subsequent glucose import during HFD-induced obesity." (PMID 27180971, 2016). "Its remodeling and dysfunction induced by obesity have been described as essential contributors to insulin sensitivity impairment." (PMID 27111539, 2016). "Overweight and obesity lead to changes in adipose tissue such as inflammation and reduced insulin sensitivity." (PMID 27821717, 2016). "LEP has been proposed as a culprit for obesity-induced cancer because it displays epigenetic variation and is involved in energy homeostasis, immune responses, angiogenesis and insulin signaling." (PMID 27703473, 2016). "Mice lacking leptin receptor in SF-1 expressing neurons specifically in the VMH exhibited metabolic syndrome features including obesity, elevated insulin and leptin levels and impaired glucose tolerance." (PMID 27598259, 2016).
Obesity (continued). "We found that adipocyte-specific CD1d deletion abrogated NKT cell activation via adipocytes and thus ameliorated inflammation in adipose tissue, resulting in reduced obesity and improved insulin sensitivity." (PMID 27329323, 2016). "Activation of the NLRP-3 inflammasome in course of diet-induced obesity in mice led to an increase in IL-18 secretion and was shown to affect insulin signaling." (PMID 26788518, 2016). "Insulin sensitizers have been proposed as a promising tool for the reduction of obesity-induced insulin resistance and inflammation processes." (PMID 27795733, 2016). "Heterozygous PPARγ mice are resistant to high fat diet (HFD) induced obesity and under these conditions, remained more sensitive to insulin than their WT counterparts." (PMID 27483259, 2016). "Among these studies, CTRP12 is an insulin-sensitizing, anti-inflammatory adipokine, downregulated by obesity." (PMID 26754066, 2016). "Adult hNAG-1 mice have reduced white adipose tissue and are resistant to obesity, show reduced inflammatory responses and increased insulin sensitivity, presumably due to increased thermogenesis and metabolic activity in the presence of circulating hNAG-1." (PMID 26745373, 2016). "Here, we report that chronic AMPK activation in mice induces hyperphagia and adult-onset obesity, with glucose intolerance and impaired glucose-stimulated insulin secretion." (PMID 27133129, 2016). "Visceral adipose tissue has been proposed to mediate obesity-related unfavourable levels of insulin, glucose and lipids, but subcutaneous abdominal adipose tissue has been shown to be independent risk factor for the metabolic complications of obesity." (PMID 26786000, 2016). "Resistance to diet-induced obesity and liver statosis are often accompanied by increased glucose tolerance and insulin sensitivity." (PMID 27456060, 2016). "We then examined if some of the characteristic features of serum in obesity (high leptin, high insulin, and high free-fatty acids) affect leptin responsiveness." (PMID 26849804, 2016). "In some recent studies, evidence has brought forth a relationship between some types of obesity and an alteration in insulin sensitivity." (PMID 27672393, 2016). "Alterations in lipids in muscle and plasma have been documented in insulin‐resistant people with obesity." (PMID 26916476, 2016). "A few studies have investigated the relationship between circulating levels of galectin-3, obesity and parameters of glucose metabolism, and insulin sensitivity in patients with diabetes." (PMID 26770660, 2016). "Drosophila studies have provided conceptual and mechanistic advances in our understanding of the role that insulin plays in obesity-related cancers." (PMID 27604692, 2016). "Using this data, we evaluated the relationship between salivary insulin and glucose concentrations and obesity and identified various clinical and biomarker predictors of elevated salivary glucose concentration by body weight category." (PMID 27069678, 2016). "T2DM is a progressive disease characterized by IR, impaired insulin secretion, increased glycogen dysplasia, and obesity, the incidence of which has been rising consistently worldwide." (PMID 26986104, 2016). "Obesity-related inflammation and impaired insulin action are tightly connected; inflammation leads to impaired insulin action, which in turn contributes to the development of metabolic abnormalities." (PMID 27098727, 2016). "We recently identified that neutralization of VEGF-C and -D in the subcutaneous adipose tissue during the development of obesity improves metabolic parameters and insulin sensitivity in mice." (PMID 27511834, 2016). "The co-existence of deregulated insulin signaling in conjunction with obesity has been recognized for decades, leading Astrup and Finer to coin the term “diabesity”." (PMID 27338371, 2016).